ADA (adenosine deaminase)
Diseases named in the same sentence as ADA in open-access papers (continued):
Sharing a sentence is not in itself a finding about the gene and the disease.
COVID-19 (13 papers, 2020 to 2026). A disease caused by infection with severe acute respiratory syndrome coronavirus 2. "First, we measured the activities of total adenosine deaminase (tADA) and its isoenzymes in the serum of post-COVID patients and non-COVID-19 individuals." (PMID 37685949, 2023). "In this study, we investigated the activities of circulating ADA isoenzymes in patients 8 weeks after mild COVID-19 and related them to the parameters of inflammation and microvascular/endothelial function." (PMID 37685949, 2023). "As we aimed in this study to characterize the relation of circulating ADA isoenzyme pattern with endothelial and microvascular dysfunction in patients after mild COVID-19, further research on the mechanical explanations of our findings are highly requested." (PMID 37685949, 2023). "This study points to the possible role of ADA isoenzymes in cardiovascular complications after mild COVID-19." (PMID 37685949, 2023). "The current paper points to the possible role of ADA isoenzymes in cardiovascular complications after mild COVID-19." (PMID 37685949, 2023). "In line with that, it was found that serum ADA activity was two times higher in patients with severe COVID-19 in comparison to moderate course of the disease." (PMID 37685949, 2023). "In conclusion, this study describes endothelial activation after mild COVID-19 and points to possible involvement of ADA isoenzymes in cardiovascular complications after recovery." (PMID 37685949, 2023). "At present, there are few studies on the changes of ADA in the serum of patients with COVID-19 and its impact on COVID-19 progression." (PMID 36211421, 2022). "One cannot exclude that the increased levels of ADA, which at least in our study were similar in the COVID-19 and PIMS groups, could also be involved in that process." (PMID 39940694, 2025). "However, suppressing ADA to augment protective adenosine was proposed to be favorable rather in improving long-term chronic clinical outcomes in COVID-19 patients than throughout the early phase of the infection." (PMID 37685949, 2023). "In another study, the nasopharyngeal specimen of SARS-CoV-2 infected patients revealed higher ADA expression level in nasopharyngeal swabs when compared with controls and, interestingly, when compared to the swabs obtained from patients with severe COVID-19." (PMID 37685949, 2023). "Thus, the current study aimed to analyze the activities of circulating ADA isoenzymes in patients after mild or asymptomatic COVID-19 and to link them with the parameters of endothelial and microvascular dysfunction." (PMID 37685949, 2023). "The enzymatic roles of ADK and ADA might be targeted to ameliorate ARDS that often is present in patients with severe COVID-19." (PMID 33324223, 2020). "It is plausible that ADA might also be involved in COVID-19 and PIMS immunology." (PMID 39940694, 2025). "Hence, inhibiting ADA to augment protective adenosine might be beneficial to improve clinical outcomes in COVID-19 patients." (PMID 33324223, 2020). "We analysed the serial MPO, ADA, CCL22, TNFα, and IL-6 mRNA expression in nasopharyngeal specimens of 154 COVID-19 and 163 control hospitalized patients in the fifth wave of COVID-19 in Hong Kong." (PMID 36482706, 2023). "In summary, the present study demonstrates the increase in nasopharyngeal MPO, ADA, CCL22, TNFα, and IL-6 mRNA expression in COVID-19 patients." (PMID 36482706, 2023). "Particularly, this study reports upregulated ADA, BTC, DPP6, EDIL3, LIF, ENTPD2, Flt3L, and LRP1 in severe COVID-19 patients for the first time." (PMID 36428847, 2022). "Saliva contains numerous additional COVID-19 indicators, including ACE2, adenosine deaminase, immunoglobulin G, immunoglobulin M, RNA, and secretory immunoglobulin A, in addition to SARS-CoV-2 virions." (PMID 36138463, 2022). "This raises the possibility of targeting ADA and ADK for prevention and/or treatment of ARDS during later phases of COVID-19." (PMID 33324223, 2020).
COVID-19 (continued). "In summary, ADA appears to be a better biomarker to differentiate between infected and uninfected patients, while CCL22 has the potential in stratifying the severity of COVID-19." (PMID 36482706, 2023). "Although there are significant differences in terms of age, co-morbidities, and blood parameters, multivariate analysis still showed that the expression of MPO, ADA, CCL22, TNFα, and IL-6 mRNA in nasopharyngeal specimens is higher in COVID-19 patients when compared with the control group." (PMID 36482706, 2023). "It is no different in COVID-19 where ADA activity was higher in saliva of symptomatic COVID-19 and 10 days after positive SARS-CoV-2 PCR than in healthy controls." (PMID 37685949, 2023). "Furthermore, this study reports markers including ADA, BTC, DPP6, EDIL3, LIF, ENTPD2, Flt3L, and LRP1 to be upregulated in severe COVID-19 patients; hence, they are proposed as novel biomarkers for severe cases of COVID-19." (PMID 36428847, 2022). "Adenosine and the key adenosine regulators adenosine deaminase (ADA), adenosine kinase (ADK), and equilibrative nucleoside transporter 1 may play a role in COVID-19 pathogenesis." (PMID 33324223, 2020). "Depending on the stage of exposure to and infection by SARS-CoV-2, enhancing adenosine levels by targeting key adenosine regulators such as ADA, ADK and equilibrative nucleoside transporter 1 might find therapeutic use against COVID-19 and warrants further investigation." (PMID 33324223, 2020). "The correlation between ADA isoenzyme pattern in the serum of post-COVID patients and the proportion of circulating monocytes should be further examined in order to assess whether ADA2 could be used as an indicator of deregulated proinflammatory cytokine production in post-COVID-19 individuals." (PMID 37685949, 2023). "Comparison of the MPO, ADA, CCL22, TNFα, and IL-6 mRNA expression between patients with and without completion of COVID-19 vaccines did not reveal any statistically significant differences." (PMID 36482706, 2023).
viral infections (13 papers, 2013 to 2025). "In conclusion, this study highlights the role of ADA in endothelial inflammation after viral infections." (PMID 40469975, 2025). "Of interest, cell-surface antibody staining did not predict/correlate with respective ADCC levels, although the same infecting virus and experimental set up was used (ADA Env WT or N-U- virus infection)." (PMID 31139189, 2019). "However, whereas the cytidine deaminase inhibits virus infection at the reverse transcription step, adenosine deaminase may affect the HIV-1replication at a post-transcription stage." (PMID 25272020, 2014). "For instance, the adenosine deaminase acting on RNA enhancer, as an adenosine deaminase that acts on RNA and suppresses IFN system responses in viral infections, is regulated by MR198-3p." (PMID 37559103, 2023). "Accordingly, ADA competed with MERS-CoV for binding to DPP4, acting as a virus–DPP4 attachment inhibitor and preventing virus infection." (PMID 36009573, 2022). "By studying SG proteins with uncharacterized impact on viral infection, we identified the virus-specific function of GILT-like, SGS1 and ADA, and the broad effect of SGBAP in reducing the infections by DENV2, ZIKV and CHIKV." (PMID 34880409, 2021). "The present study was carried out to determine the effect of a viral infection of the ENS on contractile responses to adenosine, as well as on distribution of adenosine receptors and of its enzymes CD73 and ADA in rat ileum." (PMID 24015268, 2013). "Furthermore, in adenosine deaminase ADAR1 deficiency cases, self-dsRNA can activate OAS-RNase L without viral infection, leading to Aicardi-Goutières syndrome (AGS)." (PMID 41457140, 2025). "Taken together, these findings suggest that EBNA1 contributes to the activation of ADA in some cell types, but may not be sufficient for the complete activation observed during viral infection." (PMID 33497421, 2021). "Finally, the possible role of adenosine deaminase acting on RNA (ADAR) must be taken into consideration, as these enzymes produce adenosine-to-inosine deamination in regions of the RNA, and play important roles during viral infections." (PMID 32438744, 2020). "Soluble CD26 could interfere with this role of ADA in many pathological conditions, such as obesity and several viral infections, where its concentration is highly increased, but not in healthy physiological conditions, where its concentration (up to 4 nM) is much lower than its affinity for ADA." (PMID 29497379, 2018).
hyperuricemia (12 papers, 2020 to 2025). An abnormally high level of uric acid. "We conclude that CCE has anti-hyperuricemia effects and alleviates renal inflammation in a rat model of hyperuricemia, and these efficacies are associated with the reversal of increased ADA, PNP, and JUN mRNA expression in renal tissues." (PMID 38026974, 2023). "Three genes (GARS, AIRS, and GART) involved in the de novo purine biosynthesis pathway have been mapped to chromosome 21 and excessive purine synthesis gives rise to hyperuricemia, increased plasma adenosine levels, and increased adenosine deaminase activity." (PMID 38960035, 2024). "Further, adenosine metabolism via adenosine deaminase increases the production of metabolites in the purine degradation pathway like inosine which in turn thus contributing to uric acid production and hyperuricemia." (PMID 38992061, 2024). "It suggests that the mechanism by which CCE ameliorates the inflammatory condition in hyperuricemia is closely related to its inhibitory effect on ADA inflammatory enzymes." (PMID 38026974, 2023). "Further research confirmed that CCE has the potential to regulate the mRNA expression of ADA, PNP, and JUN in the kidney, thereby alleviating hyperuricemia associated with anti-inflammatory activity." (PMID 38026974, 2023). "Therefore, lowering the activity of XO and ADA can reduce the formation of uric acid, superoxide radicals, and ammonia peroxide in the body and improve the symptoms of hyperuricemia." (PMID 38397567, 2024). "Additionally, an animal study inferred that Zn can alleviate hyperuricemia by decreasing the activities of adenosine deaminase and xanthine oxidase (XO), and promoting UA excretion by altering intestinal flora composition." (PMID 37670835, 2023). "In summary, folic acid and zinc effectively relieve hyperuricemia, on the one hand, by inhibiting the synthesis of uric acid via reducing ADA and XOD activities, and on the other hand, by promoting uric acid excretion by changing the gut microbiota composition." (PMID 35966674, 2022). "Simultaneously, serum ADA was dramatically increased in the hyperuricemia group." (PMID 32083126, 2020). "The levels of XOD and ADA in serum and hepatic tissues were found to be increased after induction of hyperuricemia, whereas the activities of hepatic XOD and ADA were significantly decreased by allopurinol but unaffected by MOS." (PMID 36678288, 2023). "In addition, UWB-H and UWA-H exhibit a significantly protective effect on the renal injury of PO-induced hyperuricemia mice, in which UWA can simultaneously reduce the activity of XOD and ADA and regulate the expression of uric acid transporter." (PMID 32083126, 2020). "Moreover, hyperuricemia mice were administered orally various parts extracts at 0.78 and 2.34 g/kg (crude drug dose converted by extraction rate) to observe the change of hepatic XOD, serum ADA, renal function, and uric acid transporter." (PMID 32083126, 2020). "Regrettably, we did not observe changes in XOD and ADA enzyme activities after MOS treatment, indicating that MOS may be anti-hyperuricemia not by affecting uric acid synthesis, but by influencing uric acid excretion." (PMID 36678288, 2023).
Sepsis (12 papers, 2008 to 2025). Sepsis is defined as life-threatening organ dysfunction caused by a dysregulated host response to infection. "The upregulation of ADA would reflect the immune system activation associated with sepsis." (PMID 36430174, 2022). "Analytes related to inflammation and immunity (ADA, Hp, and Calp), sepsis (aldolase), stress (sAA), tissue damage (LDH and TP), and redox status (AOPP) were measured to obtain a wide panel of biomarkers." (PMID 39997755, 2025). "The activity of ADA in the serum is increased during inflammatory diseases (e.g., sepsis) as a result of increased macrophages activity and the interaction of ADA with DPP-4 leads to NF-κB activation in T cells." (PMID 30619349, 2018). "Inhibition of rephosphorylation of adenosine by adenosine kinase inhibitors or its degradation by adenosine deaminase (ADA) improves survival of sepsis in various sepsis models." (PMID 18847498, 2008). "ADA increases inflammation and sepsis in the saliva of pigs." (PMID 37092455, 2023). "The inhibition of the degradation of adenosine by ADA improves survival from sepsis." (PMID 18847498, 2008). "This study predicted a total of 109 drug targets based on the Drugbank23 database using the structure of MEL, which yielded three shared sepsis‐related genes (PIK3CG, ADA, and MAPKAPK3)." (PMID 36684068, 2023). "We previously found that adenosine deaminase acting on double-stranded RNA 1 (ADAR1) plays regulatory roles in the pathology of sepsis, but the mechanism of ADAR1 in sepsis-induced pyroptosis and lung injury remains unclear." (PMID 38169584, 2024).
Hypertension (11 papers, 2012 to 2022). The presence of chronic increased pressure in the systemic arterial system. "Human studies have shown increase in ADA activity and expression in response to hypertension and hypertension-associated pathologies, such as metabolic syndrome." (PMID 30159340, 2018). "A genetic study with hypertensive patients showed that a common polymorphism (C34T) of the ADA gene (isoform 1) is strongly correlated with essential hypertension." (PMID 30159340, 2018). "Alternatively, it can be speculated that the reduction in ADA activity is one step further in the different events that ends in an AF or can be just another risk-factor for the AF, as well as high blood pressure, age, or obesity." (PMID 33801676, 2021). "It was indeed suggested that ADA activity as well as platelet aggregation could serve as peripheral markers for the development of therapy for the maintenance of homeostasis and inflammatory processes in hypertension and hypertension-associated pathologies." (PMID 30159340, 2018). "It has been observed that the decreased activity of NOS after exposure to BPA also increases the hydrolysis of ATP by the enzymes ATPase, ADPase, AMPase and the activity of adenosine deaminase (ADA) in the eye cells in arterial hypertension in rats." (PMID 36362630, 2022). "This study showed that in the experimental group, DM and hypertension markedly elevated serum ADA concentrations, whereas alcohol consumption, and smoking decreased ADA activity." (PMID 36260871, 2022). "Changes in ADA expression and activity are also related to hypertension development and maintenance." (PMID 30159340, 2018). "Franco and colleagues have analyzed the activity of nucleotidases and ADA in cytosolic and membrane fractions of renal tissue, in an angiotensin-II model of hypertension." (PMID 30159340, 2018). "ADA activity is also increased in both platelets and lymphocytes in an animal model of hypertension induced by L-NAME administration." (PMID 30159340, 2018). "We also found a tendency to increased inosine generation following adenosine supplementation by diabetic VSMCs, possibly as a result of increased ADA activity, as described in diabetic patients and in experimental models of hypertension." (PMID 26879172, 2016). "Increased serum ADA activity has been shown to be involved in various metabolic and inflammatory diseases, including atherosclerosis, thrombosis, acute myocardial infarction, hypertension, Graves’ disease, and T2D." (PMID 36267565, 2022). "As a result, testosterone boosting and the modulation of the E-NTPDase as well as ADA in the pathogenesis of hypertension may represent mechanisms by which TN and WN contribute to erectile function." (PMID 34684530, 2021). "The increase in ADA activity has been also described in hypertension." (PMID 33053898, 2020). "Besides, ginger protected against hypertension-derived complications by decreasing platelet adenosine deaminase (ADA) activity and increasing the level of adenosine, which prevented platelet aggregation and promoted vasodilation in hypertensive rats." (PMID 31151279, 2019). "In addition, patients with increased cardiometabolic risks are always characterized by elevated serum ADA levels, and these cardiometabolic risks include higher BMI, increased TC, hypertension, atherosclerosis, thrombosis, coronary artery calcification and T2D." (PMID 36267565, 2022). "We observed that ADA concentrations of ACI patients were affected by DM, hypertension, high alcohol consumption and smoking status." (PMID 36260871, 2022). "There is no data elucidating the origin of elevated ADA activity in hypertension." (PMID 33053898, 2020).
pneumonia (11 papers, 2019 to 2025). An acute, acute and chronic, or chronic inflammation focally or diffusely affecting the lung parenchyma, caused by an infection in one or both of the lungs (by bacteria, viruses, fungi, or mycoplasma.). "Other analytical data described in acute Q fever pneumonia include altered transaminases (around 20% of pneumonia cases), hyponatremia (probably related to the inappropriate secretion of antidiuretic hormone) and elevated serum ADA (adenosine deaminase) levels." (PMID 40559597, 2025). "Noninfectious pneumonia is seen in adenosine deaminase (ADA) deficiency and pulmonary alveolar proteinosis (due to CSF2RA and GATA2 deficiency)." (PMID 37102642, 2023). "Adenosine Deaminase, the key enzyme of purine metabolism catalyzing the irreversible hydrolytic deamination of adenosine to inosine is implicated in a varied spectrum of human diseases ranging from SCID to TB and pneumonia." (PMID 33883834, 2020).
asthma (10 papers, 2010 to 2025). "A severe lung inflammation with eosinophilic airway infiltration and mast cell degranulation, features found in asthma patients, have been observed in an ADA-deficient mice model." (PMID 34068999, 2021). "Many of the supporting publications suggested a relationship between ADA mutations and asthma, allergy, and immune function." (PMID 34283031, 2021). "Inosine is a key metabolite of purine metabolism that is produced from adenosine by the catabolic enzyme adenosine deaminase (ADA), which is also linked to the inflammatory response in animal models of asthma." (PMID 33919626, 2021). "ROBOKOP identified publications suggesting an association between ADA mutations and asthma, allergy, and immune function, including one publication suggesting an association with aspirin-intolerant asthma." (PMID 34283031, 2021). "Some C3 proteins are highly associated with asthma, such as: CD80 influences synthesis of IL-4 and IFN in non-specific bronchial asthma, mutations in IL12A influence cockroach allergy among children with asthma, ADA polymorphisms are related to asthma." (PMID 33008305, 2020). "Similarly, using whole blood samples, polymorphisms of ADORA3 have been identified in patients with aspirin-induced urticaria, of ADORA1 and ADORA2A in aspirin-induced asthma, both in Korean population; ADA polymorphism have been observed in asthma patients from a Chinese Han population." (PMID 34068999, 2021). "In ADA-deficient mice that naturally develop lung inflammation reminiscent of asthma, ADA enzyme therapy has beneficial effects, preventing accumulation of adenosine and mast cell degranulation." (PMID 39188525, 2024). "Mice studies have shown a relationship between ADA and an inflammatory phenotype in the lungs, similar to human asthma." (PMID 23675170, 2010). "The potential role of ADA in asthma has also been demonstrated in humans." (PMID 40929127, 2025).